CD9 (CD9 molecule)
Diseases named in the same sentence as CD9 in open-access papers (continued):
Sharing a sentence is not in itself a finding about the gene and the disease.
Arthritis (1 paper, 2024). Inflammation of a joint. "Previously, CD9 or CD81 deficiency induced protective effects on articular cartilage in rodent models of arthritis, but earlier studies on the connections of EV tetraspanins and cartilage degradation remain scarce." (PMID 38254142, 2024). "The roles of tetraspanins in arthritis remain unresolved, but their profiles have been studied in the plasma EVs of RA patients, who had higher proportions of single-positive CD81 and CD9 sEVs but lower levels of double-positive CD81/CD9 sEVs than healthy controls." (PMID 38254142, 2024).
autism (1 paper, 2009). Persistent deficits in social interaction and communication and interaction as well as a markedly restricted repertoire of activity and interest as well as repetitive patterns of behavior. "Interestingly, androgens have been shown to induce CD9 in human prostate, suggesting yet another mechanism for increased expression in autism." (PMID 19492049, 2009).
bladder tumor (1 paper, 2016). "The microarray result of sorted CD9+ cancer cells from one bladder tumor specimen showed no AGR2 expression, but showed CD10 expression." (PMID 26894971, 2016).
bronchiolitis obliterans syndrome (1 paper, 2023). A lung disorder that is mainly associated with chronic allograft dysfunction after lung transplantation and that is characterized by inflammation and fibrosis of bronchiolar walls that reduce the diameter of the bronchioles and result in progressive and irreversible airflow obstruction. "CD9-expressing B cells appear as a contributor to a favorable environment essential for the maintenance of long-term stable graft function and as a potential new predictive biomarker of bronchiolitis obliterans syndrome–free survival." (PMID 36968829, 2023).
Burkitt lymphoma (1 paper, 2022). A rare form of malignant mature B-cell non-Hodgkin lymphoma. "Exosomes isolated from EBV+ NPC cells (HK1EBV) or Burkitt’s lymphoma cells (rAkata) were characterized using microbeads conjugated with anti-CD9 antibodies, followed by examination of exosome structures using transmission electron microscopy (TEM)." (PMID 35986369, 2022).
Cachexia (1 paper, 2021). Severe weight loss, wasting of muscle, loss of appetite, and general debility related to a chronic disease. "Furthermore, we detected the exosomal markers Hsp70, TSG101, and CD9 in LLC-EVs and colon-26 (C26)-derived EVs (C26-EVs; C26 that also induce cachexia in mice) by western blotting analysis." (PMID 33510128, 2021).
cardiac ischemia (1 paper, 2024). "The sEVs, purified by ultracentrifugation (from pooled PFP of participants positive for cardiac ischemia), showed that Hsp47 was present in the sEVs as identified by CD9 in the Western blot analysis." (PMID 38732154, 2024).
cataract (1 paper, 2018). Partial or complete opacity of the crystalline lens of one or both eyes that decreases visual acuity and eventually results in blindness. "Here, we found that CD9/CD81 double knockout (DKO) mice with a COPD-like phenotype progressively developed a syndrome resembling human aging, including cataracts, hair loss, and atrophy of various organs, including thymus, muscle, and testis, resulting in shorter survival than wild-type (WT) mice." (PMID 29572511, 2018).
Cerebral ischemia (1 paper, 2021). Restriction of arterial blood supply to the brain associated with insufficient oxygenation to support the metabolic requirements of the tissue. "Here, we examined the expression levels of VCAM-1, ICAM-1, E-selectin, and CD9 in vivo and in vitro to confirm the effects of CD151 on endothelial cell adhesion molecules within the TEMs in cerebral ischemia." (PMID 34022890, 2021).
cerebral malaria (1 paper, 2017). A sequestration of Plasmodium falciparum in the brain, which can cause coma and/or seizures. "The question of whether P-selectin and CD9 play a role in cerebral malaria (CM) requires further investigation." (PMID 28642573, 2017).
chronic cholecystitis (1 paper, 2012). "HMGA2 expression of gallbladder adenocarcinoma was significantly higher than that of adjacent tissue, polyps and chronic cholecystitis gallbladder epithelium (P <0.01), but CD9 expression was the opposite (P <0.05 or P <0.01)." (PMID 22613496, 2012). "Our data showed that the CD9-positive expression ratio of gallbladder cancer was significantly lower than that of the adjacent tissues, adenomatous polyps and gallbladder epithelium of chronic cholecystitis." (PMID 22613496, 2012). "HMGA2 expression of gallbladder adenocarcinoma was significantly higher than that of adenocarcinoma adjacent tissues (= 16.13, P <0.01), polyps (= 8.19, P <0.01) and chronic cholecystitis (= 21.41, P <0.01); but CD9 expression was the opposite (P <0.05 or P <0.01)." (PMID 22613496, 2012). "The resected specimens of 108 cases of gallbladder adenocarcinoma, 46 cases of adjacent tissue, 15 cases of polyps and 35 cases of chronic cholecystitis were made into conventional paraffin-embedded sections, using the method of EnVision immunohistochemistry to stain HMGA2 and CD9." (PMID 22613496, 2012).
chronic GVHD (1 paper, 2014). "The molecules that provided the best discrimination between acute and chronic GVHD were: the activation marker CD9; adhesion molecules CD11c and CD18; chemokine receptor CCR3; and prostaglandin receptor CRTH2." (PMID 25400930, 2014).
chronic hepatitis C (1 paper, 2022). "To verify the results of the trial study, we examined the levels of the 9 proteins, IGHV, GAPDH, C1s, GRP78, V-ATPase, PPBP, CD9, Lp(a) and SAP, in EVs isolated from the sera of another 80 patients with chronic hepatitis C before DAA treatment." (PMID 35797333, 2022).
chronic lung allograft dysfunction (1 paper, 2018). Chronic lung allograft dysfunction encompasses a range of pathologies that cause a transplanted lung to not achieve or maintain normal function. "In the field of lung transplantation, we reported a persistently low level of CD9+ B cells in patients with chronic lung allograft dysfunction; conversely, patients able to restore a higher level of CD9+ B cells posttransplantation were more likely to maintain stable graft function." (PMID 30356731, 2018).
colitis (1 paper, 2017). Inflammation of the colon. "The specific role of CD9 in IBD was further dissected by transfer of CD4+ CD45RBhi naive T cells into the Rag1−/− mouse colitis model." (PMID 29312336, 2017). "Our results indicate that CD9 depletion enhances IEC proliferation, resulting in a high regenerative response and reduced susceptibility to DSS-induced colitis." (PMID 29312336, 2017). "CD9−/− mice showed less severe colitis than wild-type counterparts upon exposure to DSS (2% solution) and enhanced survival in response to a lethal DSS dose (4%)." (PMID 29312336, 2017). "To explore the function of CD9 in colitis development, we challenged CD9−/− and WT mice with the toxic compound DSS (2% solution) in drinking water for 7 days." (PMID 29312336, 2017). "To further explore possible CD9-mediated immune mechanisms in IBD, we used an alternative model of colitis induced by intraperitoneal transfer into Rag1−/− mice of CD4+CD62L+CD25−CD45RBhi naive T cells sorted from WT or CD9−/− mice." (PMID 29312336, 2017). "In this study, we investigated the role of CD9, a tetraspanin that regulates major biological processes such as cell migration and immunological responses, in two mouse models of colitis that have been used to study the pathogenesis of inflammatory bowel disease (IBD)." (PMID 29312336, 2017). "Here, we studied the role of CD9 in the pathogenesis of colitis in vivo." (PMID 29312336, 2017). "Here, we show that CD9 acts as a limiting factor for epithelial regeneration and colonic MH in dextran sodium sulfate (DSS)-induced colitis." (PMID 29312336, 2017). "Our data indicate that CD9 in non-hematopoietic cells plays an important role in colitis by limiting epithelial cell proliferation." (PMID 29312336, 2017).
colorectal tubulovillous adenoma (1 paper, 2021). A neoplasm that arises from the glandular epithelium of the colonic and rectal mucosa. "The levels of 20S proteasomes in exosomes, MMP9+, MMP9+/MMP2+/EMMPRIN+ in CD9-positive blood plasma exosomes are associated with the risk of malignant transformation of colorectal tubulovillous adenomas." (PMID 33773551, 2021).
cortical dysplasia (1 paper, 2017). "The assessment of protein expression of a wide range of markers showed that the two patients with cortical dysplasia, included in this study, express higher percentages of several neuroblast and stem cell markers including DCX, NeuN, Nurr1, CD56, CD166, CD9, CD73, CD59, CD61 and cKit." (PMID 28796246, 2017).
dengue (1 paper, 2023). "On immunoblotting, differential expression of CD63 and CD9 proteins was observed in the PLT-EXOs derived from dengue patients with different clinical presentations." (PMID 38235130, 2023). "Of note, CD63 and CD9 expression levels were significantly higher on the PLT-EXOs isolated from dengue patients than the healthy subjects." (PMID 38235130, 2023). "On quantitation, fold change expression of CD63 and CD9 in PLT-EXOs was significantly higher in all the dengue patients (p=0.02, p=0.03), WS+ (p=0.001, p=0.029) and SDG (p=0.008, p=0.02) respectively than the healthy subjects." (PMID 38235130, 2023). "Similar expression levels of CD63 and CD9 were seen when exosomes from primary and secondary dengue patients were compared." (PMID 38235130, 2023). "In summary, our results suggest that PLT-EXOs isolated from dengue patients express CD63 and CD9 at significantly higher levels than healthy subjects and disease severity is associated with the increased secretion of PLT-EXOs in dengue patients." (PMID 38235130, 2023). "PLT-EXOs isolated from the dengue patients showed higher expression of CD63 and CD9 proteins than the healthy subjects." (PMID 38235130, 2023).
diabetic nephropathy (1 paper, 2019). "To this end, we assessed CD9 glomerular expression in a model characterized with accentuated podocyte loss and glomerulosclerosis upon genetic targeting of podocyte autophagy that exacerbates diabetic nephropathy." (PMID 31341160, 2019). "Conversely, no CD9 expression was found in PECs in mouse model of diabetic nephropathy, even in a model prone to podocyte injury (i.e. Nphs2.cre Atg5lox/lox)." (PMID 31341160, 2019).
endometritis (1 paper, 2022). An acute or chronic, usually bacterial infectious process affecting the endometrium. "The EVs from mares with endometritis differentially expressed CD9 and CD63, compared to controls." (PMID 35042518, 2022). "Moreover, the EVs isolated from serum and LVL in mares suffering from endometritis were differentially expressed CD9 and CD63, compared to control healthy." (PMID 35042518, 2022). "Interestingly, the EVs isolated from serum and LVL in mares with endometritis differentially expressed CD9 and CD63, compared to control healthy ones." (PMID 35042518, 2022).
epithelioid mesotheliomas (1 paper, 2013). "Among the epithelioid mesotheliomas (EMs), CD9 expression was observed in all of the 33 cases with a differentiated type (EM-D) and in 29 of the 38 cases with a less-differentiated type (EM-LD)." (PMID 23128478, 2013). "This is supported, in part, by the fact that histologically less-differentiated epithelioid mesotheliomas showed lower CD9 expression." (PMID 23128478, 2013). "CD9 expression may be also an indicator of epithelial-mesenchymal transition from epithelioid mesothelioma to sarcomatoid mesothelioma." (PMID 23128478, 2013).
esophageal cancer (1 paper, 2025). A primary or metastatic malignant neoplasm involving the esophagus. "The results showed that compared with 32 adjacent tissues, CD9 expression was higher in esophageal cancer tissues (P=0.047)." (PMID 40860827, 2025). "Analysis of TCGA data via UALCAN revealed significantly elevated CD9 mRNA expression in esophageal cancer tissues (n=184) compared to normal esophageal samples (n=11) (P=0.0082)." (PMID 40860827, 2025). "At present, there is limited research on the role of CD9 in esophageal cancer." (PMID 40860827, 2025).
esophageal tumor (1 paper, 2021). "Immunohistochemistry (IHC) analysis showed that the expression of exosome marker CD9 in esophageal tumor tissues was much higher than that in normal tissues, confirming the existence of exosomes in EC tissue." (PMID 34561425, 2021).
essential thrombocythemia (1 paper, 2021). A chronic myeloproliferative neoplasm that involves primarily the megakaryocytic lineage. "In our study, we focused on the expression of CD9 in myeloproliferative neoplasms—specifically those linked to the JAK2 (V617F) mutation, such as polycythemia vera, and essential thrombocythemia." (PMID 33918035, 2021).
experimental autoimmune encephalomyelitis (1 paper, 2019). An autoimmune demyelinating disease of the central nervous system that is produced experimentally in animals by the injection of homogenized brain or spinal cord in Freund's adjuvant. "Encephalitogenic T cells from Myelin Oligodendrocyte Glycoprotein (MOG)-Induced Experimental Autoimmune Encephalomyelitis (EAE) mice showed significantly lower levels of TSPAN32 and increased levels of CD9, CD53, CD82 and CD151." (PMID 31487788, 2019).
gallbladder adenocarcinoma (1 paper, 2012). A carcinoma that arises from glandular epithelial cells of the gall bladder. "The data also suggest the prognostic significance of HMGA2 and/or CD9 expression as a tumor biological marker in patients with gallbladder adenocarcinoma." (PMID 22613496, 2012). "The expression of HMGA2 and/or CD9 might be closely related to the carcinogenesis, clinical biological behaviors and prognosis of gallbladder adenocarcinoma." (PMID 22613496, 2012). "In the present study, our data showed that the expression of HMGA2 and/or CD9 might be closely related to carcinogenesis, clinical biological behaviors, and prognosis of gallbladder adenocarcinoma." (PMID 22613496, 2012).
gallbladder cancer (1 paper, 2012). "CD9 also reflected progression and clinical behaviors of the gallbladder cancer and was the important biological marker of prognosis." (PMID 22613496, 2012). "Cox multivariate regression analysis showed that the HMGA2 positive expression and/or CD9 negative expression was an important indicator reflecting the poor prognosis of gallbladder cancer." (PMID 22613496, 2012).
gastric tumor (1 paper, 2014). "These negative results contrast with another model of gastric tumor implantation in SCID mice treated with the mAb ALB6 (IgG1) directed against tetraspanin CD9 that resulted in inhibition of tumor growth associated with increased apoptosis and reduced angiogenesis." (PMID 25285080, 2014).
gastric ulcer (1 paper, 2011). An ulcerated lesion in the mucosal surface of the stomach. "All normal gastric epithelium and gastric ulcer tissues strongly expressed transcripts of CD9, CD63 and CD82." (PMID 21521534, 2011). "All normal gastric epithelium and gastric ulcer tissues strongly expressed transcripts and proteins of CD9, CD63 and CD82 as compared with corresponding controls." (PMID 21521534, 2011). "All normal gastric epithelium and gastric ulcer tissues were strongly expressed immunostaning of CD9, CD63 and CD82." (PMID 21521534, 2011).
gastrointestinal stromal tumor (1 paper, 2012). "Recent research suggests that CD9 can be potential prognostic markers of gastric GIST and may serve as novel therapeutic targets of gastrointestinal stromal tumor (GIST)." (PMID 22634835, 2012).
glomerulonephritis (1 paper, 2019). A renal disorder characterized by damage in the glomeruli. "Given the strong association between de novo glomerular CD9 expression and CGN, we next investigated the role of CD9 during glomerulonephritis in the murine NTS-induced CGN model." (PMID 31341160, 2019). "Given the coexpression of CD9 with the activated-PEC marker CD44 during proliferative glomerulonephritis, we next investigated whether CD9 was involved in other diseases with PEC phenotypic changes, like FSGS35,36." (PMID 31341160, 2019).
glomerulosclerosis (1 paper, 2019). A hardening of the kidney glomerulus caused by scarring of the blood vessels. "Silencing Cd9 not only reduced PEC-induced glomerulosclerosis but also maintained the number of podocytes." (PMID 31341160, 2019).
heart failure (1 paper, 2023). Inability of the heart to pump blood at an adequate rate to meet tissue metabolic requirements. "Similar to a recently described population of fibrosis-associated liver macrophages,35SPP1+ macrophages specifically expressed TREM2 and CD9 in both CKD and heart failure." (PMID 36807143, 2023).
hemangioma (1 paper, 2020). A benign vascular lesion characterized by the formation of capillary-sized or cavernous vascular channels. "However, more research is needed to clarify the role of CD9 on hemangiomas." (PMID 32094357, 2020).
Hepatic steatosis (1 paper, 2024). Steatosis is a term used to denote lipid accumulation within hepatocytes. "Analysis of fatty livers from both humans and mice provided clinical and basic pathological insights into the association of decreased CD9 levels with hepatic steatosis, a correlation that was functionally validated by liver CD9 knockdown in vivo and in vitro." (PMID 38837628, 2024). "Current study revealed that hepatic deficiency of CD9 exacerbated diet‐induced liver steatosis via complement factor D regulated fatty acid metabolism." (PMID 38837628, 2024). "Deficiency of CD9 in the liver exacerbated diet‐induced hepatic steatosis via complement factor D (CFD) regulated fatty acid metabolism." (PMID 38837628, 2024). "Taken together, these findings suggest that CD9 deficiency accelerates hepatic steatosis through enhancing fatty acid synthesis and suppressing oxidation under HFD." (PMID 38837628, 2024). "Based on our present study, we uncover an essential role of CD9 in counteracting hepatic steatosis, and highlight it as a mediator of the hepatic effects of GCGR agonist." (PMID 38837628, 2024). "Hepatic CD9 reinforcement alleviated liver steatosis, and blockage of CD9 abolished the remission of hepatic steatosis induced by cotadutide treatment." (PMID 38837628, 2024). "Moreover, CD9 reinforcement in the liver alleviated hepatic steatosis, and blockage of CD9 abolished the remission of hepatic steatosis induced by cotadutide treatment." (PMID 38837628, 2024). "Take together, our study reveals the essential role of CD9 in counteracting liver steatosis." (PMID 38837628, 2024). "Moreover, our findings propose that CD9 might serve as a potential therapeutic target for MASLD, which was evidenced by that the restoration of CD9 attenuated lipid accumulation and hepatic steatosis." (PMID 38837628, 2024). "Liver‐specific CFD deletion abrogated CD9 effects, and overexpressed CFD induced consistent hepatic steatosis observed in CD9 knockdown mice." (PMID 38837628, 2024). "CD9 medicates the hepatic beneficial effects of GCGR signaling, and may server as a promising therapeutic target for hepatic steatosis." (PMID 38837628, 2024). "Additionally, our study highlights CD9 as a mediator of GCGR agonist's hepatic benefits, and may server as a promising therapeutic target for liver steatosis." (PMID 38837628, 2024). "Thus, CD9 medicates the hepatic beneficial effects of GCGR signaling, and may server as a promising therapeutic target for hepatic steatosis." (PMID 38837628, 2024).
hepatoblastoma (1 paper, 2021). Hepatoblastoma (HB) is a malignant hepatic tumor and is the most common pediatric liver cancer. "The other hepatoblastoma tumor showed positivity for CD10, CD9, CD81, CD105 in the absence of GD2, EpCAM, CD99, numyogenin, and CD90." (PMID 34638431, 2021).
histiocytic sarcoma (1 paper, 2016). An aggressive malignant neoplasm with a poor response to therapy, usually presenting as stage III/IV disease. "Finally, upregulation of GTSF1, LUM, and PYPH and downregulation of CLEC12A and CD9 in primary canine histiocytic sarcomas were found to be dysregulated similarly in 3132 cells." (PMID 27639374, 2016).